SPP1 (secreted phosphoprotein 1)
Diseases named in the same sentence as SPP1 in open-access papers (continued):
Sharing a sentence is not in itself a finding about the gene and the disease.
cancer (continued). "Notably, SPP1 alone as well as the CM of macrophages alone promoted cancer cell re-growth." (PMID 36139536, 2022). "However, SPP1 was strongly positive in both the cancer cells and TAMs in some cases." (PMID 36139536, 2022). "However, the expression profile and oncogenic features of SPP1 in diverse cancers are remaining unknown." (PMID 35067176, 2022). "In addition, we revealed that the SPP1 expression was related to cancer immunity." (PMID 35067176, 2022). "Besides, high expression of SPP1 is correlated with poor survival in several cancers." (PMID 36038839, 2022). "However, the expression levels of SPP1 in some cancers were controversial." (PMID 36585688, 2022). "Moreover, using the same single-cell RNA-seq dataset, we evaluated SLC7A11-positive macrophages in other cancer types with SPP1-positive macrophages, a poor prognostic factor based on previous studies, because Spp1 was also detected in our 26 commonly upregulated genes." (PMID 36470862, 2022). "Therefore, SPP1 expression could be a valuable prognostic biomarker, because SPP1 upregulation resulted in a significant decrease in patient survival in certain cancer types." (PMID 35067176, 2022). "In addition, SPP1 knockdown attenuated NET-induced migration in cancer cell lines." (PMID 35432310, 2022). "In addition, we analyzed information from The Cancer Genome Atlas (TCGA) dataset, and the results showed that both the ESCA carcinoma and adenocarcinoma tissue had a higher SPP1 expression compared to normal tissue, while the carcinoma tissue had the highest SPP1 expression." (PMID 35593388, 2022). "Overexpression of SPP1, a protein involved in ECM adhesion during wound healing, is also associated with cancer progression, metastasis, and apoptosis inhibition, just like an upregulation of the transmembrane sorting protein SORL1 that promotes cell proliferation in cancer cells." (PMID 33690729, 2021). "Upregulated expression of growth factors such as IGF1, FGF7, proteases such as MMP2, ECM constituents such as SPP1 also known as osteopontin and chemokine such as CXCL12 may indicate the presence of cancer-associated fibroblasts (CAFs) within the tumor microenvironment." (PMID 34946170, 2021). "Indeed, our pan-analysis showed that a number of cancers were characteristic of SPP1 upregulation." (PMID 33996808, 2021). "Each SPP1 isoform is characterised as a potential prognostic marker for multiple malignancies, such as lung, breast, and ovarian cancers; however, they cannot be used as universal markers for cancer prognosis based on the variance in their expression and associated signalling among tissues." (PMID 32503462, 2020). "In addition, in more than three types of cancer, the group with low SPP1 expression had no common mutated gene (data unshow)." (PMID 33324676, 2020). "Several mechanisms by which SPP1 could be involved in cancer progression have been suggested." (PMID 20859289, 2010). "Overall, this review aims to provide a comprehensive overview of the mechanisms mediated by SPP1+ TAMs in the TME, and emphasize their unique role in cancer progression." (PMID 41751193, 2026). "SPP1, a secreted glycoprotein, binds to the CD44 receptor on cancer cells, activating key pathways like PI3K/AKT, FAK, and NF-κB." (PMID 40076844, 2025). "In terms of cellular crosstalk, SPP1+ TAMs express SPP1 and nicotinamide phosphoribosyl transferase (NAMPT) to interact with the stroma and cancer cells." (PMID 41341850, 2025). "Three (SPP1, CALR, and PRDX2) of the four enriched biomarkers in this study were found to be expressed mainly in cancer cells." (PMID 39939411, 2025). "Similarly, the ligand‐receptor pairs SPP1‐ITGA5_ITGB1, SPP1‐ITGA8_ITGB1, SPP1‐ITGA9_ITGB1, as well as SPP1‐ITGAV_ITGB1, were also identified in the communications of both cancer cells and T cells with VasECs specifically in BM, as well as in the communications of senescent cancer cells with VasECs." (PMID 39231761, 2025).
cancer (continued). "A 2023 study reported the presence of SPP1-expressing TAM in alpha-fetoprotein-positive HCC tissues and demonstrated that SPP1 can inhibit the anti-cancer activity of T cells by binding to CD44." (PMID 38757323, 2025). "The cancer cell modules (I) of the two samples are characterized by distinct marker genes, i.e., PMEL, ATP1A1, and SPP1 in sample 1 whereas S100B and PSAP in sample 2, in line with previous studies." (PMID 40033360, 2025). "These contrasting interpretations underscore the complexity of defining SPP1+ TAM identity and function across cancer types and highlight the importance of context‐specific investigations." (PMID 40395129, 2025). "The increase in putrescine content leads to the SPP1 and OPN overexpression in macrophages, conferring cancer stemness to OC cells through the OPN-CD44 axis." (PMID 41271556, 2025). "Rather than a SPP1 population expanding only after seeding of metastatic cancer cells, we postulate a mechanism linking primary extrahepatic tumors to premetastatic expansion of an intrahepatic TGF-βR + IL6R + SPP1-KC intermediate macrophage population." (PMID 40335453, 2025). "In BC tissues, TAP1, PILRA, UBE2C, TMEM51, and MKI67 were significantly upregulated, while the expression levels of SPP1 and CENPF remained unchanged between cancer and adjacent tissues." (PMID 41328437, 2025). "We also integrated and reclustered CRLM and HCC macrophage data and found that the proportion of SPP1+ macrophages was significantly lower in HCC than in CRLM samples, indicating that the elevation of SPP1+ macrophages is cancer-type specific." (PMID 40092488, 2025). "In this context, we propose four potential biomarkers, SPP1, LTF, CARL, and PRDX2, for the early detection of MDSC‐dominant cancer." (PMID 39939411, 2025). "Consequently, even in the event that highly specific SPP1-targeted therapeutics become available, their clinical application will necessitate the development of precision treatment strategies that are tailored to the particular cancer type, molecular context, and stage of disease progression." (PMID 41391064, 2025). "YBX1, known for its role in various cancers, and G3BP1, an RNA-binding protein often found in tumors, form a complex in renal cell carcinoma that activates SPP1 and the NF-κB pathway." (PMID 41391064, 2025). "Further research indicates the interaction between SPP1 and CD44 is a key mechanism in maintaining cancer stem cell characteristics and enhancing chemotherapy resistance." (PMID 41391064, 2025). "According to a study, MIF was found to regulate secreted phosphoprotein 1 (SPP1) and increase TAM migration to HCC cells, and resulted in increased cancer metastasis and invasion." (PMID 41159021, 2025). "Both SPP1 and MIF are known contributors to critical cancer hallmarks, including cell growth, survival, metastasis, migration, and angiogenesis." (PMID 39505867, 2024). "This subpopulation demonstrated high expression levels of the cancer stem cell markers POU5F1 and CD44 (POU5F1hiCD44hiE.T), with the transcription factor POU5F1 regulating the expression of SPP1." (PMID 38191424, 2024). "Despite this potential, anti-cancer drugs that target MIF (Imalumab: NCT01765790) and SPP1(BET inhibitors) are still in the exploratory or early clinical trial phase." (PMID 38191424, 2024). "SPP1 binds to various receptors, including CD44 which has been recognized as an essential cell surface marker of cancer stem cells, driving treatment resistance and poor prognosis in various tumors." (PMID 38491408, 2024). "Adding another layer to the intricacies of cancer treatment, the secreted phosphoprotein 1 (SPP1), also known as osteopontin (OPN), exhibits upregulation in malignancies, correlating with treatment resistance." (PMID 38398072, 2024). "SPP1 and IL6 followed a similar trend, with only elevated detection levels in cancer, suggesting their involvement in colorectal cancer." (PMID 39523395, 2024).
cancer (continued). "The immunohistochemical analysis revealed significantly higher expression of CD44, MYC, IL17A, CXCL1, FCGR3A, SPP1, and IL1A in cancer tissues, while CXCL12 and CCL5 showed significantly higher expression in adjacent normal tissues." (PMID 39767563, 2024). "These ligand–receptor interactions were primarily involved in JAM, SPP1, gelatin and ECM, including fibronectin and collagen; these molecules play a crucial role in the regulation of EMT in cancers." (PMID 39001509, 2024). "Our results extend these implications to PDAC, highlighting the importance of the spatially correlated crosstalk between CTHRC1+GREM1+ myCAF and SPP1+APOE+ TAM that drive fibrosis, immunosuppression, and EMT in PDAC and potentially other cancers." (PMID 39075108, 2024). "Recognizing the crucial role of T cells in the cancer-immunity circle, intercellular interactions centered around T cells were highlighted within the CCL, SPP1, and CXCL pathways." (PMID 38550593, 2024). "Another transcription factor, FOSL1, is also expressed by Macro_SPP1 and is known to regulate invasion and metastasis, linking with EMT and cancer cell stemness." (PMID 38521868, 2024). "Eight hub genes (MMP1, MMP7, MMP13, LAMC2, LAMB3, PLAU, COL7A1, and SPP1) were upregulated in both HNSCC and LSCC, suggesting a significant role in cancer progression." (PMID 38707175, 2024). "C1QC+ TAMs and SPP1+ TAMs have also been identified in PDAC, and were found to share similar characteristics with those in other human cancers." (PMID 39507421, 2024). "In terms of gene expression, SPP1, IKBKE, CXCL11, CXCL10, and other genes showed extensive high expression in COAD, ESCA, KIRC, READ, UCEC, and other cancers." (PMID 37666853, 2023). "The authors identified CD44+ CAF EndMT - Spp1+ TAM interactions in promoting EndMT process and angiogenesis leading to poor prognosis in cancer patients." (PMID 37342322, 2023). "Secreted phosphoprotein 1(SPP1), an extracellular secreted glycol phosphoprotein is closely related to the biological processes of multiple types of cancer, such as proliferation, and migration." (PMID 37259059, 2023). "The expression of SPP1 in different tumors and normal tissues by PAN cancer analysis on the TIMER website revealed that SPP1 is highly expressed in almost all tumors." (PMID 36688087, 2023). "Spp1 was elevated by both the HFD and the cancer cells in the OFB; the HFD also elevated the cancer-mediated increase in Spp1 expression in the OFB and, to a lesser extent, in the pmWAT and rpWAT." (PMID 38264656, 2023). "In this study, SPP1 was found to up-regulate in HNSCC tissues and was supposed to be a promoting-cancer biomarker." (PMID 37185487, 2023). "This pancancer gene set includes key integrins (e.g. ITGA6, ITGB1, ITGB4) and their interconnectors (e.g. SPP1, TGFBI), affirming their critical role in the cancer adhesion resistome." (PMID 37206618, 2023). "Consistently, previous studies have shown that SPP1, APOE, C1QA, C1QB, and C1QC are significantly elevated in the plasma of patients with cancer." (PMID 37187751, 2023). "The expression of LPCAT1, NDRG1, G6PD, CYP7A1, SPP1, SFN, and CDCA8 was significantly higher in cancer tissues than in paraneoplastic tissues, whereas the expression of DNASE1L3 was significantly lower in cancer tissues." (PMID 37717019, 2023). "SPP1 also activates ROCK signaling via the FAK/PI3K/AKT pathway, thereby facilitating cancer invasion through lamellipodia formation." (PMID 35453667, 2022). "CRC patients in both TCGA and GSE17536 CRC cohorts with a higher infiltration of SPP1+ macrophages exhibited shorter PFS, and the infiltration correlated with late-stage cancer and MSI-H patients in the TCGA CRC cohort." (PMID 35365629, 2022). "SPP1 was found to be highly expressed and correlated with NET formation in cancers with poor survival." (PMID 35432310, 2022). "Therefore, SPP1 may serve as an attractive target in cancer mechanistic research and in treatment." (PMID 35067176, 2022).
cancer (continued). "To validate the relationships between PDAI5 and immune pathways in cancers, we investigated the effect of PDIA5 on the programmed death-1 (PD-1)/PD-L1 signaling pathway and SPP1 signaling pathway." (PMID 36003400, 2022). "Following Cd exposure, the direction of the most differentially expressed genes such as SPP1, MMP3 and SULF1 in fibroid cells favored cellular migration, proliferation and cancer progression as predicted by IPA pathway analysis." (PMID 35453667, 2022). "Specifically, M1 and M2 macrophages targeted other cells in the GALECTIN, GRN and SPP1 signaling pathway networks, and GBM cancer cells regulated other cells in the MK and PTN signaling pathway network." (PMID 35558067, 2022). "By contrast, the FN1-related molecular pairs, including FN1-CD44 (a marker of cancer stem cells) and FN1-(ITGAV + ITGB1), were prompted between SELENOP-Mφ/SPP1-Mφ and FABP4-Mφ/FCN1-Mφ/CD4/CD8 cells in LUAD." (PMID 36008393, 2022). "LAMA1, CHAD, ITGA8, and COL11A1 consistently showed hypermethylation in more than half of cancer types; on the contrary, TNN, SPP1, COL6A6, and TNR consistently showed hypomethylation in more than half of types of cancer." (PMID 36311789, 2022). "MRNA expression of SPP1, VEGFA, POSTN, CD44, FOXO1, and RUNX2 genes was significantly change with the cancer stages of the patients." (PMID 36424413, 2022). "Several publications have reported the relationships between these five ER-related genes (SPP1, KIF2C, LPCAT1, KPNA2, and FMO3) and cancers." (PMID 35915607, 2022). "The most enriched KEGG pathways were related to the ribosome (RPS5, RPS9), focal adhesion signaling pathways (FGL, SPP1), synaptic vesicle cycle (CLTC), and ether lipid metabolism (ENPP2), which were related to the invasion and metastasis of cancer." (PMID 36276156, 2022). "The Pearson R value between SPP1 and NET score showed that SPP1 had a positive correlation with NET score only in cancer types with poor NET-related survival (GBM, R = 0.576; OV: R = 0.494)." (PMID 35432310, 2022). "Collectively, we found that SPP1 was highly expressed and correlated with NET score in cancer types with poor NET-related survival." (PMID 35432310, 2022). "The expression of TNFAIP3 was higher in immune cells, especially in epithelial carcinoma, macrophages, and CD8+ T‐cells (left), while TGFBI, IFI30, SPP1, and EREG were expressed more highly in macrophages than other cells." (PMID 35634956, 2022). "Blocking antibodies to SPP1 and its specific receptors CD44 showed an inhibitory role in cancer cell migration." (PMID 34676217, 2021). "Consistently, SPP1 was enriched in ECM receptor interaction according to KEGG pathway analysis, which plays crucial role in cancer metastasis." (PMID 33892811, 2021). "Western blot demonstrated that ATG10, PRKCD, and SPP1 were highly expressed in cancer tissues, while IL18RAP and SLC11A1 expression in cancer tissues was lower." (PMID 34631695, 2021). "These 8 genes (SPP1, TTK, MELK, FOXM1, LYN, ARRB2, COL6A3, and CCL21) were further validated in more numbers of cancer tissue samples by quantitative real-time PCR (qRT-PCR)." (PMID 33829064, 2021). "As SPP1+ TAMs were revealed to harbor higher hypoxia score and co-occur with EMT cancer cells, we focused on exploring the functions of SPP1 and SPP1+ TAMs." (PMID 34676217, 2021). "Similar to the findings of our study, it has been reported that secreted phosphoprotein 1 (SPP1) is a cancer-related gene, which presents clearly upregulated level in many cancers." (PMID 33892811, 2021). "SPP1, also known as OPN, is a well-known factor with critical roles in osteoclastogenesis and cancer-related osteolysis." (PMID 34556636, 2021). "SPP1 expression in myeloid cells along with EMT and glycolysis program in cancer cells was higher in hypoxia-high samples." (PMID 34676217, 2021). "The involvement of IGFBP1, TIMP1, SPP1, IGFBP3, and STC2 in mediating chemotherapy resistance in various cancers have been extensively studied." (PMID 34737677, 2021).
cancer (continued). "In Elyada’s scRNA-seq analysis, ductal cancer cells in human PDAC were clustered in two major subtypes: the classic (by TFF1, TFF2, LYZ, VSIG2, and CEACAM6 marker genes) and secretory (by SPP1, CLU, CTGF, and COL18A1 marker genes) subtypes." (PMID 34035226, 2021). "Genes in the regulation of the insulin-like growth factor transport pathway have known functions in cancer proliferation and migration, including IGFBP5, PRSS23, SCG2, and SPP1." (PMID 35008167, 2021). "In the meantime, SPP1 overexpression promotes the expression of KLF4, NANOG, SOX2, and BMI1, which were cancer stem cell markers." (PMID 33996808, 2021). "Among the DEGs in myeloid cells, SPP1 and TIMP1 were the most significantly upregulated genes in hypoxia-high cells across cancers." (PMID 34676217, 2021). "Among the universal DEGs, 4 upregulated genes (BGN, E2F3, PLAU, and SPP1) and 1 downregulated gene (UBL3) were found to be cancer genes already documented in the COSMIC or F-Census databases." (PMID 33542925, 2021). "The interactive analysis tool was applied to confirm the expression level of the eight DEGs (SPP1, TTK, MELK, FOXM1, LYN, ARRB2, COL6A3, and CCL21) in cancer and normal tissues." (PMID 33829064, 2021). "Secreted phosphoprotein 1 (SPP1) [also designated as osteopontin (OPN)] mediates critical processes involved in cancer progression, including immune response, cell adhesion and migration, and tumourigenesis." (PMID 32503462, 2020). "Our results consistent with these reports and indicated that SPP1 has a more important correlation with CD44 and ITGB1 in selected cancer contrast to adjacent normal tissue." (PMID 33324676, 2020). "Secreted Phosphoprotein 1 (SPP1), also known as osteopontin, is one of the molecules in the PI3K/AKT/mTOR pathway, and it has been reported as an oncogene in many cancers." (PMID 33193731, 2020). "Whatever, this finding is the first report indicating SPP1 as the predictor to independently predict OS and RFS for pan-cancer." (PMID 33324676, 2020). "The expression of SPP1 in normal lung tissue and LUAD was analyzed from the Cancer Cell Line Encyclopedia (CCLE), Gene Expression Omnibus (GEO), and Human Protein Atlas (HPA) databases." (PMID 32595698, 2020). "Each osteomimetic marker harbored prognostic value in the pan-cancer analyses [SPARC: hazard ratio (HR) = 1.10, p = 0.028; SPP1: HR = 1.25, p < 0.001; BGLAP: HR = 1.13, p = 0.005]." (PMID 33240930, 2020). "Secreted phosphoprotein 1 (SPP1), also called Osteopontin (OPN), has been demonstrated overexpressed in many cancers." (PMID 33324676, 2020). "We found two genes, DCN and SPP1, showing different expression in AEM compared to either AEC or advanced carcinoma." (PMID 33322258, 2020). "Statistical significance was found when comparing expression of DCN and SPP1 in AEM and advanced carcinoma (p < 0.001 in both cases)." (PMID 33322258, 2020). "Consistently, mRNA expression levels of YAP target genes such as cyclin E, SPP1, and CTGF were up-regulated in CD133− cancer cells following rhHMGB1 treatment." (PMID 31558702, 2019). "SPP1, also known as osteopontin, an ECM proteinis involved in tumorigenesis and cancer progression and has been shown to be a key role of PCa metastasize to the bone (Desai, Rogers & Chellaiah, 2007)." (PMID 31637138, 2019). "Among the identified HDAC6-RUNX2 target genes we found SPP1, a consolidated RUNX2 target involved in cancer cells migration and invasiveness." (PMID 31395086, 2019). "Further research is required to confirm these results and verify the value of SPP1 and SPP2 as clinical markers of cancer prognosis." (PMID 31849319, 2019). "Inhibition of JNK activity provides an opportunity to repress simultaneously the expression of SPP1 and TNC in the cancer cells." (PMID 30190333, 2018). "Identification of the niche matrix components SPP1 and TNC as relevant mediators of therapy resistance highlights the significance of the ECM as a valuable source of cancer targets." (PMID 30190333, 2018).